RERG (RAS like estrogen regulated growth inhibitor)
Description:
Binds GDP/GTP and possesses intrinsic GTPase activity. Has higher affinity for GDP than for GTP.
Synonyms: MGC15754
Tractability: Small molecule: a structure with a bound ligand is known. Antibody: its Gene Ontology location is reachable by antibodies, with medium confidence. PROTAC: ubiquitination databases record sites on it.
Gene: Protein-coding gene on chromosome 12 (15,107,783 to 15,348,675, reverse strand). Ensembl gene ENSG00000134533.
Subcellular location: Cytoplasm
Subcellular location (Human Protein Atlas): Cytosol; Nucleoplasm; Nucleoli fibrillar center
Gene Ontology:
Molecular function: GTPase activity; protein binding; GDP binding; nuclear estrogen receptor binding; G protein activity; GTP binding
Biological process: negative regulation of cell growth; negative regulation of cell population proliferation; response to hormone; establishment or maintenance of cell polarity; Ras protein signal transduction; small GTPase-mediated signal transduction
Cellular component: cytoplasm; cytosol; nucleus; plasma membrane
Genetic constraint (gnomAD): Loss-of-function variants: 17 observed, 16.64 expected, observed/expected ratio (o/e) 1.02, 90% interval 0.7 to 1.53. The upper end of that interval is the gene's LOEUF score, 1.53, which puts it in group 6 of 6, group 1 being the genes least tolerant of losing a copy. Missense variants: 190 observed, 186.68 expected, observed/expected ratio (o/e) 1.02, 90% interval 0.9 to 1.15. Synonymous variants: 58 observed, 66.87 expected, observed/expected ratio (o/e) 0.87, 90% interval 0.7 to 1.08.
Homologues: Orthologues: macaque RERG (100% identical), chimpanzee RERG (99% identical), dog RERG (99% identical), guinea pig RERG (99% identical), mouse Rerg (98% identical), pig RERG (98% identical), rabbit RERG (98% identical), rat Rerg (98% identical), tropical clawed frog rerg (89% identical), zebrafish RERG (72% identical). Paralogues in human: RASL11A (38% identical), RERGL (36% identical), RASL11B (35% identical), RIT1 (35% identical), RIT2 (35% identical), RRAS2 (35% identical), RASL12 (34% identical), RAP1A (33% identical), RAP1B (33% identical), KRAS (33% identical), NRAS (32% identical), RRAD (32% identical), and 23 more.
Diseases named in the same sentence as RERG in open-access papers:
RERG is named in the same sentence as 30 diseases in open-access papers, as found by Europe PMC text mining. Sharing a sentence is not in itself a finding about the gene and the disease. The quoted sentences say what the papers report.
breast carcinoma (19 papers, 2016 to 2024). "Intriguingly, TXNIP and RERG have also been reported to be linked to breast cancer suppression associated with better prognosis." (PMID 38282415, 2024). "We chose to focus on the association of RERG with NFAT3 because previous studies have associated RERG expression with better survival in luminal breast cancer patients and revealed its capacity to inhibit cell invasion." (PMID 35847954, 2022). "RERG is a growth-inhibitory gene highly expressed in luminal breast cancer and is associated with the longest survival of luminal breast cancer patients without metastases." (PMID 35847954, 2022). "This revealed the functional association between NFAT3 and RERG in the T-47D luminal breast cancer cell line." (PMID 35847954, 2022). "In breast cancer, high RERG protein expression was associated with longer disease-specific survival and distant metastasis-free interval independently of other prognostic variables." (PMID 33540554, 2021). "RERG was initially identified as a tumor suppressor gene in breast cancer, and RERG overexpression showed an association with better prognosis in ER-positive luminal-like subtype." (PMID 33015704, 2020). "Loss of RERG has been implicated in the induction of breast cancer growth, but the detailed mechanism is still unclear." (PMID 27705918, 2017). "Because miR-382-5p targeted and repressed RERG, an estrogen-regulated tumor suppressor gene, it made a connection between the oncogenic role of miR-382-5p and the estrogen-associated nature of breast cancer." (PMID 27705918, 2017). "This novel connection highlights new diagnostic and prognostic roles for miR-382-5p and RERG in breast cancer." (PMID 27705918, 2017). "Importantly, we validated the association of NFAT3 with RERG in luminal breast cancer tissues from patients and disclosed that a higher amount of this complex, in the primary tumor, was observed in patients lacking axillary lymph node colonization." (PMID 35847954, 2022). "We have validated the association of NFAT3 with RERG in human luminal breast cancer tissues." (PMID 35847954, 2022). "RERG gene expression is stimulated by both estrogen receptor (ER) α and ERβ1, and it has been reported as a marker for ERα-positive luminal-like breast cancer and is associated with better clinical outcomes or a favorable response to adjuvant tamoxifen treatment." (PMID 27705918, 2017). "Here, we report that NFAT3 specifically interacts, at least via its last 85 C-terminal amino acids, with RERG in the luminal breast cancer cell line T-47D." (PMID 35847954, 2022). "Some studies have reported that RERG is an inhibitor of the MAPK/ERK pathway, a pathway implicated in breast cancer cell migration." (PMID 35847954, 2022). "Indeed, because of the dominant negative effect of the last 85 amino acid C-terminal of NFAT3 on the invasive capacity of this luminal breast cancer cell line, we hypothesized co-factor binding to this specific region to inhibit cell invasion and revealed its association with RERG." (PMID 35847954, 2022). "Among these putative prognostic markers, RERG, a growth-inhibitory gene highly expressed in luminal breast cancer, was correlated with the estrogen-regulated longest survival of luminal breast cancer patients without metastases." (PMID 35847954, 2022). "We further validated the NFAT3 interaction with RERG by PLA assays in luminal breast cancer tissues obtained from patients with (10 patients) or without (11 patients) distant ALN metastases at diagnosis." (PMID 35847954, 2022). "It has been demystified that knockdown of miR-23 abates the growth of breast cancer in vivo and that miR-382 triggers breast cancer metastasis by activating Ras/ERK signaling pathways via targeting RAS-like estrogen-regulated growth inhibitor (RERG)." (PMID 33066509, 2020). "As for its specific role in different breast cancer subtypes, early in 2011, RERG has been screened out as a specific biomarker for ER-positive luminal, like breast cancer subtype." (PMID 31480430, 2019).
breast carcinoma (continued). "A research group found that microRNA-382-5p aggravates breast cancer progression by regulating the RERG/Ras/ERK signaling axis." (PMID 29692777, 2018). "Recent studies also showed that estrogen up-regulate the expression of RERG a novel tumor suppressive gene which is highly expressed in ER + ve breast cancers." (PMID 29843638, 2018). "Previous studies suggested that HIF-1α- or TGFβ1-induced miR-382-5p expression led to the inhibition of the ERβ-RERG tumor suppressive signaling cascade in breast cancer." (PMID 27705918, 2017). "The Ras GTPase superfamily member RERG (Ras-related and estrogen-regulated growth inhibitor) acts as a tumor suppressor to reduce breast cancer cell proliferation and tumor formation and has been suggested to have a regulatory role in the Ras/ERK pathway." (PMID 27705918, 2017). "There were 27 candidates predicted in both databases, but only RERG was reported as a tumor suppressor gene in breast cancer." (PMID 27705918, 2017). "In contrast, RERG was significantly downregulated in carcinoma in situ, invasive and metastastic breast cancer cells, and more highly expressed in benign breast diseases." (PMID 27705918, 2017). "MiR-382-5p expression negatively correlated with RERG expression, and higher miR-382-5p expression was an independent oncomiR for the higher morbidity and mortality of breast cancer." (PMID 27705918, 2017). "Although ERα had been reported to activate RERG gene expression, we found that lower RERG was significantly associated with poorer OS and DFS in both ERα (+) and ERα (−) breast cancer subtypes." (PMID 27705918, 2017). "In clinical interpretation, miR-382-5p expression was negatively correlated with RERG expression, and it also significantly functioned as an independent oncomiR for the higher incidence and poorer prognosis of breast cancer." (PMID 27705918, 2017). "It has been reported that RERG is a prognostic marker in breast cancer, and its expression has correlated inversely with proliferation, patient survival, and the development of distant metastases." (PMID 28659184, 2017). "RERG has been reported to play a tumor suppressor role in the inhibition of breast cancer cell proliferation and tumor formation." (PMID 27705918, 2017). "miR-382-5p can aggravate breast cancer development through regulating RERG/Ras/ERK signaling." (PMID 34258298, 2021). "To examine whether RERG compensative expression attenuated the oncogenic effects of miR-382-5p on breast cancer cell viability and progression, we co-transfected pcDNA3-RERG or empty vector with miR-382-5p mimics or mNC into MCF-7 cells." (PMID 27705918, 2017). "MiR-382-5p, the primary microRNA species of miR-382, had an oncomiR role in breast cancer initiation and progression by directly targeting and repressing RERG, an estrogen-regulated RAS superfamily GTPase member, which had previously been implicated in regulating Ras/ERK signaling activation." (PMID 27705918, 2017). "It has been reported that RERG was involved in Ras/MEK/ERK signaling pathway in breast cancer." (PMID 28659184, 2017). "Our findings highlighted the miR-382-5p/RERG/Ras/ERK axis in breast cancer and may partially explain the different roles for miR-382-5p among different cancer types." (PMID 27705918, 2017). "In conclusion, miR-382-5p plays an oncogenic role in breast cancer initiation and progression by directly targeting and repressing RERG, thereby activating the Ras/ERK pathway to promote cancer cell viability, clonogenicity, survival, migration, invasion and in vivo tumorigenesis/metastasis." (PMID 27705918, 2017). "RERG was reported to be a tumor suppressor gene in colorectal cancer and breast cancer." (PMID 28716111, 2017). "RERG is a tumor suppressor gene that was first reported in breast cancer." (PMID 28659184, 2017).
breast carcinoma (continued). "Consequently, RERG was expressed in a reciprocal pattern with miR-382-5p, as RERG was expressed at lower levels in more poorly differentiated breast cancer cell lines compared to H184B5F5/M10 cells." (PMID 27705918, 2017). "We further propose that miR-382-5p inhibition or RERG overexpression could effectively treat breast cancers with a hyperactive Ras/ERK pathway." (PMID 27705918, 2017). "In addition, the distribution of either miR-382-5p or RERG was significantly different between benign breast disease controls and breast cancer cases (p < 0.001 for miR-382-5p, and p = 0.009 for RERG, chi-square test)." (PMID 27705918, 2017). "RERG expression is used to differentiate luminal types of breast cancer and prognostic subgroups." (PMID 28257124, 2017). "We confirmed that this NFAT3/RERG complex, via the NFAT3-Cter region, was functional and necessary for NFAT3 to impede invasion in the human luminal T-47D breast cancer cell line." (PMID 35847954, 2022). "Noteworthy was that a handful of genes from this network had been annotated as TSGs either specifically in relation to breast cancer (GATA3, RERG, and SIAH2) or in other types of cancer (DOC2A and RGS22)." (PMID 32605588, 2020). "And miR-382-5p exerted its oncogenic regulation by directly targeting and repressing RERG, thereby activating the Ras/ERK pathway to promote cell viability and more aggressive breast cancer behaviors." (PMID 27705918, 2017). "In addition, RERG has been reported to be a direct transcriptional target of ERβ1, a potential tumor suppressive estrogen receptor in breast and several other cancer types, which may strengthen the estrogen inductive tumor suppressive role of RERG in breast cancer." (PMID 27705918, 2017). "ARHGDIB, RERG, and TMEM170B were also related to breast cancer, implying they might participate in the development of mammary glands." (PMID 36685960, 2022). "Microarray analysis on breast cancer HEK293 cell lines expressing or non-expressing ERβ identified RERG as one of the primary target genes of ERβ activation." (PMID 33540554, 2021). "Machine learning analyses of invasive breast carcinomas found that RERG was one of the highest ranked genes able to differentiate between ER+ luminal-like and ER- non-luminal breast cancers." (PMID 33540554, 2021). "RERG was shownto play a regulatory role in the Ras/ERK pathway.miR-382-5p directly represses RERG; therefore, miR-382-5p promotes viability, survival, migration andinvasion of breast cancer cells." (PMID 31606975, 2020).
colorectal cancer (6 papers, 2017 to 2025). A primary or metastatic malignant neoplasm that affects the colon or rectum. "Abnormal expression of RERG is associated with tumorigenesis, progression, and metastasis, with downregulation observed in several cancer types, including colorectal cancer." (PMID 40893943, 2025). "It has been found that RERG is hypermethylated and downregulated in colorectal carcinoma, and the fact that loss of Tks4 resulted in a further reduction in RERG expression is in line with the increased invasion capacity of the Tks4 KO cells." (PMID 36674824, 2023). "RERG is a negative regulator of cell proliferation that is a close family member of the RERGL gene affected by a rare structural variation of 12p12.3 that increases familial colorectal cancer risk." (PMID 28257124, 2017).
nasopharyngeal carcinoma (6 papers, 2017 to 2024). A carcinoma arising from the nasopharyngeal epithelium. "RERG has been found frequently silenced by promoter CpG methylation in nasopharyngeal carcinoma, where it acts as a functional tumor suppressor by suppressing the extracellular signal‐regulated kinase (ERK)/NF-κB signaling pathway." (PMID 33540554, 2021). "Among these candidates, we revealed higher methylation rates of RAS-like estrogen-regulated growth inhibitor (RERG) in biopsy specimens of nasopharyngeal carcinoma more conveniently by using restriction enzyme-based real-time PCR." (PMID 30340457, 2018). "RERG is frequently silenced by promoter CpG methylation in nasopharyngeal carcinoma and inhibits the metastatic process and angiogenesis of NPC by mediating ERK/NF-κB signaling pathway." (PMID 39048806, 2024).
breast tumor (2 papers, 2017 to 2022). "Ras-like estrogen-regulated growth inhibitor (RERG) was initially identified as a candidate tumor suppressor gene, and is regulated by estrogen in breast tumors." (PMID 28659184, 2017). "Together these results provide new insights in the anti-tumoral effects of NFAT3 and its association with RERG and also highlight the potential value of the detection of the NFAT3/RERG association in luminal breast tumor patients as an indicator of the ALN status." (PMID 35847954, 2022).
glioma (2 papers, 2020 to 2023). A benign or malignant brain and spinal cord tumor that arises from glial cells (astrocytes, oligodendrocytes, ependymal cells). "Its overexpression inhibits cell proliferation through RERG/Ras/ERK signalling but promotes glioma progression via glioma microRNA-1288-3p." (PMID 36844873, 2023).
asthma (1 paper, 2024). "In addition, our MAGMA analyses implicated another four pleiotropic genes—RERG, RBM6, SDK1, and HLA-B as potential targets for further investigation into asthma and GERD." (PMID 39223263, 2024). "After comparison, asthma and GERD were found to share six genes (ERBB3, RBM6, HLA-B, SDK1, RERG, RAB5B), one of which, ERBB3, was also significantly associated with both eczema and GERD." (PMID 39223263, 2024).
carcinosarcoma (1 paper, 2022). A malignant tumor composed of a mixture of carcinomatous and sarcomatous elements. "Interrogating Uterine Corpus Endometrial Carcinoma (TCGA-UCEC) and Uterine Carcinosarcoma (TCGA-UCS) cohorts revealed NCL to be the most highly upregulated gene in carcinosarcoma, with S100A11, LMNB2, RERG, E2F1 and CCNA2 representing key dysregulated NAGs in EC." (PMID 35682908, 2022).
colon tumor (1 paper, 2017). "RERG is widely expressed in multiple normal tissues, while RERG expression is lost in breast, kidney, ovary, and colon tumor tissues." (PMID 28659184, 2017).
endometriosis (1 paper, 2020). The growth of functional endometrial tissue in anatomic sites outside the uterine body. "A genome-wide comparative analysis of ERβ-binding and gene expression in human endometriosis and endometrial tissues identified the Ras-like estrogen-regulated growth inhibitor (RERG) and serum and glucocorticoid-regulated kinase (SGK1) as key ERβ targets." (PMID 32316608, 2020).
gastric cancer (1 paper, 2020). A primary or metastatic malignant neoplasm involving the stomach. "Therefore, further biological experiments in vivo and in vitro are required to confirm the functions of OGN, JAM2, RERG, OLFML2B and ADAMTS1 genes in gastric cancer in the future." (PMID 33015704, 2020).
lung adenocarcinoma (1 paper, 2021). A carcinoma that arises from the lung and is characterized by the presence of malignant glandular epithelial cells. "Examination of TCGA datasets demonstrated that CT-RERG transcription is significantly correlated with PTPRO and RERG promoter hypermethylation in lung adenocarcinoma tissues." (PMID 34462486, 2021).
migraine (1 paper, 2025). "Genes shared between Overall migraine and MA included RERG (PoPS Score Overall: 0.50, MA: 0.94), associated with neuroinflammatory pathways, and CELSR3 (PoPS Score Overall: 0.12, MA: 0.09), involved in planar cell polarity." (PMID 40826382, 2025).
prostatic carcinoma (1 paper, 2021). "In another study, ERK5 was able to promote prostatic carcinoma cell proliferation and migration by inhibiting RERG protein expression." (PMID 33540554, 2021).
viral infection (1 paper, 2018). "Expression of Ras-like estrogen regulated growth inhibitor (RERG) increased while expression of Interleukin 22 receptor subunit alpha 1 (IL22 RA1) genes decreased in bats with WNS, irrespective of viral infection." (PMID 30341341, 2018).